HLA-DQA2 (major histocompatibility complex, class II, DQ alpha 2)
Diseases named in the same sentence as HLA-DQA2 in open-access papers:
HLA-DQA2 is named in the same sentence as 45 diseases in open-access papers, as found by Europe PMC text mining. Sharing a sentence is not in itself a finding about the gene and the disease. The quoted sentences say what the papers report.
COVID-19 (8 papers, 2021 to 2026). A disease caused by infection with severe acute respiratory syndrome coronavirus 2. "GO term analysis of the top 20 DEGs matched to the antigen processing function as indicated by significant increase of HLA-A and HLA-DQA2 in the severe group, which correlates to a previous association with COVID-19 severity." (PMID 35899045, 2022). "Notably, the macrophage-associated state in COVID-19 was dominated by an IFN-γ response with upregulation of CD163 and HLA-DQA2, contrasting sharply with the type I/III interferon signature reported in European cohorts." (PMID 42195327, 2026). "HLA–DQA2 gene expression may have a trend similar to that in patients with mild COVID-19 and recovered individuals after vaccination." (PMID 36936955, 2023). "Furthermore, we found significant downregulation of most of HLA class II genes (HLA-DRB5, HLA-DQB1 and HLA-DQA2, etc.)in B cells from COVID-19 patients, especially in the severe and acute necrotizing encephalopathy groups, indicating dysregulated crosstalk between adaptive immune cells." (PMID 37848421, 2023). "Therefore, HLA–DQA2 may be altered in expression after COVID-19 vaccination." (PMID 36936955, 2023). "Compared to mild cases, severe COVID-19 showed upregulated CD40 together with downregulated CD83, HLA-DQA2 and FCER1A in all three tissues." (PMID 34502134, 2021). "Seven of our significant genes higher (GALNT14, OAS1, CCRL2, OAS3, CCR1, OAS2, SIPA1L2) in COVID-19 and two lower (HLA-DPB1, HLA-DQA2) were identified to overlap." (PMID 34335605, 2021). "In lung, CD40, CD80, CD83 and HLA-DQA2 were upregulated while CD86 and FCER1A were decreased in mild COVID-19 as compared to healthy controls." (PMID 34502134, 2021). "The dysregulation of DC function in COVID-19 was also presented by the expression of the maturation marker (CD83), T-cell stimulation molecules (CD40, CD80, CD86) and antigen presentation molecules (HLA-DQA2 and FCER1A)." (PMID 34502134, 2021). "Finally, higher levels of KLF6, a transcription factor induced by TGF-β in DCs, was increased in pDCs in BAL from severe COVID-19 patients, while the MHC class II molecule HLA-DQA2 displayed lower transcript levels, in line with lower protein levels of HLA-DR detected on circulating pDCs." (PMID 33479167, 2021).
rheumatoid arthritis (8 papers, 2011 to 2024). A chronic, systemic autoimmune disorder characterized by inflammation in the synovial membranes and articular surfaces. "HLA-DQA2 was also associated with rheumatoid arthritis, but less frequently reported in CAD." (PMID 25514790, 2014). "HLA-DQA2, functioned as antigen presentation and likely expressed in human B lymphoblastoid cell lines, has been associated with autoimmune disorders such as type 1 diabetes, rheumatoid arthritis and alopecia areata." (PMID 22125590, 2011). "As with the original DMG-alone analysis, the MEGs were also significantly 3.75-fold enriched in the KEGG ‘Rheumatoid arthritis‘ pathway (q = 1.70E-02, where q is a multiple-test corrected P-value) with 7 out of 89 genes: ANGPT1, CSF2, CTLA4, HLA-DQA1, HLA-DQA2, HLA-DRA and HLA-DRB1." (PMID 25901943, 2015).
autoimmune disease (5 papers, 2010 to 2024). A disorder resulting from loss of function or tissue destruction of an organ or multiple organs, arising from humoral or cellular immune responses of the individual to their own tissue constituents. "An intergenic single-nucleotide polymorphism (SNP), rs9275596, located between the HLA-DQB1 and HLA-DQA2 genes, is in significant association with various autoimmune diseases according to genome-wide association studies (GWASs)." (PMID 32244438, 2020). "Within this chromosome, HLA-DQA1, HLA-DRB6, HLA-DQA2, HLA-DQB2, HLA-DRB1, and HLA-DQB1-AS1 were notable for having causal associations among several autoimmune diseases." (PMID 39590325, 2024). "Interestingly, HLA-DQA2 is known to be involved in pro-inflammatory CD4(+) T-cell-mediated autoimmune diseases such as MS and type 1 diabetes." (PMID 20426824, 2010).
type 1 diabetes (4 papers, 2010 to 2016). "Whereas in our pathway analysis, more genes are identified as part of Type I diabetes mellitus and Allograft rejection pathways (i.e. CD28, HLA-B, HLA-C, HLA-DMB, HLA-DPA1, HLA-DQA2, HLA-DRA, IL12A)." (PMID 22046267, 2011).
asthma (3 papers, 2017 to 2024). "This raises the possibility that the AOA class II CS1 variants in our study may also be associated with asthma hospitalizations and severity due to their effects on HLA-DQA2 expression." (PMID 35606880, 2022). "To further investigate the relevance of the PWAS Hub to gain insights on asthma etiology, we navigate to the gene view of HLA-DQA2." (PMID 39406500, 2024). "While previous asthma GWAS have implicated the classical and highly polymorphic HLA-DQA1 and HLA-DQB1 class II genes, our study revealed associations with HLA-DQA2 and HLA-DQB2 genes in risk for AOA." (PMID 35606880, 2022). "These analyses indicate that the most significant asthma locus in AOA is due to variation in two credible sets, whose effects are likely attributable to their impact on expression of the HLA-DQA2 and HLA-DQB2 genes and of the HLA-DQA1*03:01 allele." (PMID 35606880, 2022).
Sepsis (3 papers, 2021 to 2024). Sepsis is defined as life-threatening organ dysfunction caused by a dysregulated host response to infection. "By revealing a causal link between sepsis and CFHR5, FCER2, GZMB, HLA-DQA2, MBL2, or MPO, our study offers an essential resource for additional investigations on the subject." (PMID 39252215, 2024). "MBL2 (odds ratio [OR] = 1.046) was a risk factor for sepsis, while the other proteins (FCER2: OR = 0.922; GZMB: OR = 0.908; CFHR5: OR = 0.858; HLA-DQA2: OR = 0.896; MPO: OR = 0.875) were safety factors." (PMID 39252215, 2024).
allergies (2 papers, 2011 to 2018). "We found both shrimp and peach allergy to be associated with variants that are eQTLs for HLA-DQA2 gene expression as well as associated with specific HLA-DRB1 and HLA-DQB1 alleles." (PMID 29348432, 2018). "Additionally, both allergies’ associated variants were eQTLs for several HLA genes, with HLA-DQA2 the single eQTL gene shared between the two traits." (PMID 29348432, 2018).
diabetes (2 papers, 2022 to 2024). "In the combined analysis of genes unique to DR and those in common with diabetes mellitus at the threshold of <0.05, we identified C2, C4A, CD8A, HLA-DRB5, and HLA-DQA2, which have been associated with lymphocyte-mediated immunity (FDR 2.96 × 10−2)." (PMID 38791494, 2024). "Several diabetes risk variants increased the expression of genes in multiple tissues, including AP3S2 (rs4932265-T), CCDC92 (rs7978610-G), HLA-DQA2 (rs601945-G) and a lncRNA RP11-252K23.2 (rs3115960-G)." (PMID 35568807, 2022).
sarcopenia (2 papers, 2020 to 2025). Progressive decline in muscle mass due to aging which results in decreased functional capacity of muscles. "Analysis of non-coding variants within the HLA region, which are involved in the expression and regulation of HLA (HLA-DRB1, HLA-DQA2), and the Endoplasmic Reticulum unfolded protein stress response (AFT6B), has shown an association with these variants and sarcopenia." (PMID 30772894, 2020). "MMP24‐AS1, HLA‐DRB6, HLA‐DQA2, DDX42, BAG6, NUSAP1, LINC00940, NME1‐NME2 and AS3MT in the amygdala region showed detrimental effect on all the five sarcopenia‐related traits, whereas HLA‐DRB1, HLA‐DQB1‐AS1 and C6ORF3 showed protective effect (p < 0.05)." (PMID 39535371, 2025). "The over‐expression of nine genes (MMP24‐AS1, HLA‐DRB6, HLA‐DQA2, DDX42, BAG6, NUSAP1, LINC00940, NME1‐NME2 and AS3MT) in the amygdala region showing detrimental effect on all the five sarcopenia‐related traits, whereas three genes (HLA‐DRB1, HLA‐DQB1‐AS1 and C6ORF3) showing protective effect." (PMID 39535371, 2025).
Cachexia (1 paper, 2022). Severe weight loss, wasting of muscle, loss of appetite, and general debility related to a chronic disease. "B cells from patients with cachexia showed lower expression of MHC-II molecules (HLA-DRB5, HLA-DQA2) and higher expression of the immunoglobulins (IGHG2, IGHG3, IGKC), and genes involved in BCR signaling." (PMID 36376273, 2022).
glioma (1 paper, 2022). A benign or malignant brain and spinal cord tumor that arises from glial cells (astrocytes, oligodendrocytes, ependymal cells). "Then, via LASSO and Cox regression analyses, immune signatures were constructed using HLA-DQA2, HOXA3, and SAA2, and IDH1mt-glioma patients were divided into high-risk and low-risk groups." (PMID 36159801, 2022). "In conclusion, an immune signature constructed using HLA-DQA2, HOXA3, and SAA2 exhibited significant and specific prognostic value for IDH1mt glioma, while the high-risk group classified by the signature had a high benefit from ICB." (PMID 36159801, 2022). "Furthermore, ROC analysis was performed to determine the diagnostic value of HLA-DQA2, HOXA3, and SAA2 in the survival of IDH1mt-glioma patients, and all showed remarkable diagnostic value (AUC = 0.832, 0.896, and 0.857)." (PMID 36159801, 2022). "IHC was performed to detect the expression of HLA-DQA2, HOXA3, and SAA2 in glioma tissues, and high expression of HLA-DQA2, HOXA3, and SAA2 was observed in glioma tissues in the short-term group compared with that in the long-term group." (PMID 36159801, 2022). "We then performed a multivariate Cox regression analysis, and the immune signature constructed using HLA-DQA2, HOXA3, and SAA2 was found to act as an independent prognostic factor for glioma patients with IDH1mt, with an HR of 1.203." (PMID 36159801, 2022). "A multivariate Cox analysis also indicated that HLA-DQA2, HOXA3, and SAA2 were independent predictors of survival in glioma patients with IDH1mt." (PMID 36159801, 2022). "Therefore, the gene expression information of HLA-DQA2, HOXA3, and SAA2 and the survival information of glioma patients with IDH1mt in TCGA were imported into R software to construct a risk model." (PMID 36159801, 2022). "In this study, we focused on the IDH1mt subtype glioma and found that the risk model constructed using HLA-DQA2, HOXA3, and SAA2 showed remarkable prognostic value for IDH1mt glioma in both TCGA and CGGA cohorts but not for wtIDH1-glioma." (PMID 36159801, 2022).
influenza (1 paper, 2023). An acute viral infection of the respiratory tract, occurring in isolated cases, in epidemics, or in pandemics; it is caused by serologically different strains of viruses (influenzaviruses) designated A, B, and C, has a 3-day incubation period, and usually lasts for 3 to 10 days. "Polymorphism near HLA-DQA2 has previously been associated with mild influenza (H1N1) susceptibility, whereas HLA-DRB5 associates with RA, white blood cell counts, and a dozen other traits." (PMID 36793127, 2023).
lung carcinoma (1 paper, 2022). "Previous studies indicated that HLA-DQA2 mutations were associated with the susceptibility of lung cancer." (PMID 36159801, 2022).
metastatic tumors (1 paper, 2022). "However, macrophages in metastatic tumors had high expression of HLA-DQA2, KRT15, S100A8, and S100A9, and GO analysis showed that lipid catabolic process, myeloid leukocyte migration, and the regulation of cell activation were highly enriched." (PMID 36569924, 2022).
Moyamoya disease (1 paper, 2025). Moyamoya disease (MMD) is a rare intracranial arteriopathy involving progressive stenosis of the cerebral vasculature located at the base of the brain causing transient ischemic attacks or strokes. "Additionally, studies have suggested an association between HLA‐DQA2 and Moyamoya disease in the Chinese Han population." (PMID 39535371, 2025).
myasthenia gravis (1 paper, 2025). Myasthenia gravis (MG) is a rare, clinically heterogeneous, autoimmune disorder of the neuromuscular junction characterized by fatigable weakness of voluntary muscles. "Consistent with our study, HLA‐DQA2 has been implicated in susceptibility to myasthenia gravis." (PMID 39535371, 2025).
neuropathy (1 paper, 2024). A disorder affecting the nervous system that manifests with pain, tingling, numbness, and/or muscle weakness. "HLA-DQA2 expression levels are related to insulin-like growth factor (IGF) levels and neuropathy status in T2DM patients." (PMID 39916961, 2024).
psoriasis (1 paper, 2011). An autoimmune condition characterized by red, well-delineated plaques with silvery scales that are usually on the extensor surfaces and scalp. "SNP rs2858881 in HLA-DQA2 (OR = 1.72 to1.98, P = 1.08e-03 to 1.18e-2) were also consistently included in all regression models, while it is not significant in single SNP association in previous GWAS of psoriasis." (PMID 22125590, 2011). "With four regression models obtained, two SNPs rs9468925 in HLA-C/HLA-B and rs2858881 in HLA-DQA2 were repeatedly selected in all models, suggesting that multiple loci outside PSOR1 locus were associated with psoriasis." (PMID 22125590, 2011). "In addition to classical HLA genes such as HLA-C, HLA-B and HLA-DQA2, we also find association of non-HLA genes in the MHC region such as POU5F1, NFKBIL1, NOTCH4, MICA, IER3 and OR12D2 with psoriasis." (PMID 22125590, 2011).
pulmonary edema (1 paper, 2019). Accumulation of fluid in the lung tissues causing disturbance of the gas exchange that may lead to respiratory failure. "Our finding was consistent with positive selection of HLA loci (HLA-DRA, HLA-DQB1/HLA-DQA2) in Ethiopian population and significantly associated with the high-altitude pulmonary edema of HLA-DR6 and HLA-DQ4." (PMID 31827636, 2019).
viral infection (1 paper, 2024). "Our data suggest that individuals with high HLA-DQA2 expression are better at preventing the onset of a sustained viral infection." (PMID 38898278, 2024).
tumor (12 papers, 2017 to 2024). "HLA-C, which belongs to HLA-I and can present endogenous tumor antigens to kill tumor cells effectively, was less expressed in the high-risk group, while HLA-II, such as HLA-DPB2, HLA-DQB2, HLA-DOA, and HLA-DQA2, showed an increase in the high-risk group." (PMID 35754846, 2022). "Reduced expression of HLA is one key mechanism by which tumours escape host immune surveillance, and our SMR analyses identified decreased expression of HLA-DQA2 is linked to increased BCC risk." (PMID 33549134, 2021). "Based on marker genes for every cluster, we revealed one set of lymphatic endothelial cells (cluster 9, TFF3 +) and nine sets of vascular endothelial cells (FLT1 +): One was mostly interface-derived (clusters 2; HLA-DQA2 +) and three were mostly tumor-derived (clusters 4, 6 and 8; ROBO1 +)." (PMID 37644609, 2023). "Cluster Fib_5 prominently expressed MHC-II genes (HLA-DQA1, HLA-DQA2, HLA-DQB1, HLA-DRB5, HLA-DRB1, HLA-DRA, HLA-DPA1, and HLA-DPB1), indicating their role as antigen-presenting cells with tumor-suppressing effects." (PMID 37533434, 2023). "A reclustering analysis of macrophages distinguished macrophages into two cell types, M1 (HLA-DQA2+) and M2 (CD163+), among which the tumor-infiltrating macrophages were primarily of the M2 type." (PMID 35894206, 2022). "Moreover, FCGR2B, HLA-DQA2, and LTF are involved in tumor or organ transplantation." (PMID 35755170, 2022). "In our comparison of differentially expressed genes in DCs between non-obese tumor samples and obese tumor samples, we observed significantly lower expression of certain MHC class II molecules, such as HLA-DQA2 and HLA-DRB5, in obese CRC compared to non-obese CRC." (PMID 38311726, 2024).
cancer (4 papers, 2015 to 2021). A tumor composed of atypical neoplastic, often pleomorphic cells that invade other tissues. "Genes such as human leukocyte antigen (HLA) complex genes HLA-DQA2/HLA-DQB2 encoding HLA-Class II molecules, cancer/testis (CT) antigen XAGE1B and FOLR genes, which are related to multiple cancers, were steadily upregulated in advanced stage." (PMID 33000418, 2021). "They correspond to 63 unique genes, as some genes are prioritized in different cancers (e.g., ECT2L and HLA-DQA2 are prioritized in all four cancers), highlighting that different cancers share some rewired genes." (PMID 30778056, 2019).
infection (2 papers, 2024 to 2025). The state of being infected such as from the introduction of a foreign agent such as serum, vaccine, antigenic substance or organism. "This study identified HLA-DQA2 (associated with MHCII antigen presentation) as a predictor of infection outcome and protection." (PMID 40750594, 2025). "High expression of HLA-DQA2 before inoculation was associated with preventing sustained infection." (PMID 38898278, 2024). "At the day before viral inoculation, HLA-DQA2 expression in blood immune and nasopharyngeal cells was higher in participants in whom the virus did not succeed in establishing a sustained infection." (PMID 38898278, 2024).
HLA-DQA2 also shares sentences with these, for which no sentence is quoted: breast carcinoma (3 papers); systemic lupus erythematosus (3); melanoma (2); schizophrenia (2); adenocarcinoma (1); alopecia areata (1); berylliosis (1); bipolar disorder (1); cervical cancer (1); diabetic retinopathy (1); food allergy (1); Hypertension (1); knee osteoarthritis (1); lung adenocarcinoma (1); lung squamous cell carcinoma (1); lupus nephritis (1); membranous nephropathy (1); myocardial infarct (1); osteoarthritis (1); Primary immunodeficiency (1); psoriatic arthritis (1); sarcoidosis (1).